CD47 (CD47 molecule)
Diseases named in the same sentence as CD47 in open-access papers (continued):
Sharing a sentence is not in itself a finding about the gene and the disease.
infection (continued). "Phenotypically, CD8+ TILs of Cd47−/− mice showed a significant decrease of CD44+ effector phenotype and a concomitant increase of CD62L+ phenotype, consistent with our finding in the context of LCMV Cl13 infection." (PMID 36105746, 2022). "However, when the infection was persistent with LCMV-Cl13, on the 25th day of infection, we observed a significant decrease of CD8+ T cells in Cd47−/− mice." (PMID 36105746, 2022). "The expression levels of IFITM3, ZFP313, DDIT4, and CD47 were rapidly upregulated in the early stage of infection, though not very highly." (PMID 33614762, 2021). "Incubation of viruses and pseudoviruses produced in CD47-expressing cell lines with a blocking anti-CD47 monoclonal antibody did not affect infection levels." (PMID 34097709, 2021). "On day 46 post-LCMV Cl-13 infection, viral titers in sera dropped in both strains of mice, indicating that CD47 is not required for resolution." (PMID 30643501, 2018). "However, flow cytometric analysis of LCMV Armstrong infected mice at day 8 post infection revealed a significant decrease in the frequency of NK1.1+ and NKp46+ populations in spleens of Cd47−/− compared to WT mice." (PMID 30643501, 2018). "An overall increase of NK1.1+NKp46− cells in LCMV Cl-13 infected Cd47−/− mice was also evident on day 46 post infection with the increase of NK1.1+ population but no change in the NK1.1+NKp46+ population." (PMID 30643501, 2018). "The expressions of Slamf2 and Smalf6 were also comparable between WT and Cd47−/− NK cells after infection (data not shown), also indicating an intact MHC-1 independent NK cell activation." (PMID 30643501, 2018). "Global gene expression profiling of the host cells during infection with RSV or HPIV3 revealed increased transcription of carcinoembryonic antigen-related cell adhesion molecules (CEACAM1), CD47, fibronectin, interferon-stimulated genes and many other host cell adhesion molecules." (PMID 23742656, 2013). "As peak CD47 expression occurred 12 h post-infection in vitro, tumors were harvested 12 h post-intratumoral administration of 1 × 108 plaque-forming units (PFU) of NDV-expressing luciferase (NDV-Luc), and CD47 and GFP expression levels were assessed by flow cytometry." (PMID 41322194, 2025). "While characterizing the activation status of CD8+ T cell, we found at least a 10-fold increase in the effector phenotype (CD44+) and a concomitant decrease in the naïve phenotype (CD62L+) that was evident on the 8th day of infection and with no apparent difference between WT and Cd47−/− mice." (PMID 36105746, 2022). "Indeed, we show that Vpu-mediated CD47 downregulation leads to an enhanced capture and phagocytosis of infected CD4+ T cells by MDMs, a process that ultimately facilitates productive infection of macrophages." (PMID 34425695, 2021). "Taking advantage of a Jurkat cell line expressing human-mouse chimeric CD47, which is relatively unresponsive to Vpu modulation, we validated that Vpu-mediated CD47 downregulation contributes to phagocytosis of HIV-1-infected CD4+ T cells by MDMs and facilitates productive infection of MDMs." (PMID 34425695, 2021). "Similarly, assessment of intra-erythrocytic ROS activity and RBCs premature ageing, evaluated with the DCFDA and anti-CD47 antibody gmeanFI respectively, did not reveal major differences between control and HE-preconditioned RBCs, after HE treatment or during infection." (PMID 26465787, 2015). "Infection with WT HIV-1 resulted in an ∼30% decrease in surface CD47 levels on infected cells compared to bystander GFP cells or cells infected with dU HIV-1, suggesting that modulation of CD47 by Vpu did not involve BST2." (PMID 34425695, 2021). "Our previous data on SIRPα-CD47 have suggested that cognate receptor–ligand interactions also regulate NKT cell retention on infected KCs, with the induced expression of SIRPα after infection being preferentially, but not exclusively observed on infected KCs." (PMID 29636754, 2018).
infection (continued). "Thus, infection of reticulocytes by P. vivax may not lead to CD47 oxidation and the switch from “do not eat me” to “eat me” signal would not take place, whereas during infection of mature RBC CD47 may be well oxidized." (PMID 25158979, 2014).
hematological cancers (29 papers, 2017 to 2026). "CD47, also called integrin-associated protein, is a transmembrane immune checkpoint protein on the surface of solid and hematologic cancer cells, whose overexpression is related to poor clinical prognoses." (PMID 33422072, 2021). "Many clinical trials involve CD47‐targeting antibodies or recombinant proteins to block the CD47‐SIRPα signal in patients with advanced solid tumors or hematological cancers." (PMID 41354057, 2025). "Ongoing clinical studies have been conducted to inhibit the CD47–SIRPα axis using several antibodies or fusion proteins targeting CD47 and SIRPα in some solid and hematologic cancers." (PMID 37894750, 2023). "Anti-CD47 mAbs and selective SIRPα blockers had similar efficacy in hematologic cancers, with ORRs of 29.8% and 23.0%, respectively (p=0.48, DCR p=0.69)." (PMID 36439116, 2022). "In our analysis, greater response was seen in hematologic cancers, with similar rates for both anti-CD47 mAbs and selective SIRPα blockers." (PMID 36439116, 2022). "CD47 antibody directly induces apoptosis in cultures of several types of hematopoietic cancer cells." (PMID 34363319, 2021). "Clinical trials testing the monoclonal anti‐CD47 antibody have been carried out in a variety of solid cancers and hematopoietic cancers." (PMID 34363319, 2021). "Clinical trials using anti-CD47 mAbs or CD47-Fc fusion proteins are on-going for the treatment of hematological cancers or refractory solid tumors in combination with anti-PD-1 therapy or with anti-CD20 (Rituximab®) to target B cells." (PMID 33050070, 2020). "Monoclonal antibodies targeting CD47 are also under investigation in two Phase I trials on advanced solid and hematologic cancers (NCT02678338 and NCT02367196)." (PMID 31750244, 2019). "The premise arising from this finding is that only hematopoietic cancers that express high levels of SLAMF7 are suitable targets for CD47 blocking therapy." (PMID 30710089, 2019). "Various solid and hematologic cancers exploit CD47 expression in order to evade immunological eradication, and its overexpression is clinically correlated with poor prognoses." (PMID 28077173, 2017). "Although several SIRPα-CD47 inhibitors have shown a good efficacy in hematologic cancers, combination therapies with agents such as cetuximab, rituximab, azacitdine, avelumab are recommended, as the antitumor activity of SIRPα-CD47 inhibitors is less pronounced in solid tumors." (PMID 40050933, 2025). "However, accumulating evidence shows that solid and hematologic tumor cells overexpress CD47 to escape immune surveillance." (PMID 34584838, 2021). "Furthermore, clinical studies demonstrated the significance of blocking the CD47/SIRP interaction in animals bearing xenograft models with a variety of hematological cancers, such as acute myeloid leukemia, myelodysplastic syndrome, and refractory non-Hodgkin lymphoma." (PMID 38033495, 2023). "In vitro, macrophages can eliminate various opsonized solid and hematological cancer cell types via ADCP, which can be further promoted by treatment with anti-CD47 mAbs." (PMID 35884427, 2022). "All target cell lines tested, which included both epithelial and hematopoietic cancer cell lines (DLD1, Raji, MC38) expressed the SIRPα ligand CD47." (PMID 33133093, 2020). "We have developed a novel small molecule CD47 antagonist, AU7R-104, as therapeutic agent for solid and hematological cancers." (PMID 30400822, 2018). "A number of potent CD47 inhibitors are currently available (e.g. Hu5F9-G4, CC-90002, TTI-621, NI-1701, NI-1801, SRF231) and some of them are already under clinical investigation in human solid and hematological cancers." (PMID 30653520, 2019). "Thus, CD47-CAR-T cells and humanized CD47-CAR-T cells can be a novel type of cellular therapy for solid and hematological cancers." (PMID 29065481, 2017).
blood cancers (12 papers, 2020 to 2024). "CD47 was the first DEMs antigen identified and it was found upregulated and prognostically relevant in both solid and blood cancers." (PMID 37654003, 2023). "Since CD47 is upregulated in both solid and hematological tumors and such overexpression is correlated with poor patient survival or poor response to therapy, several CD47-SIRPα antagonists were developed and are currently active in clinical trials." (PMID 35158779, 2022). "Early data emerging from these trials suggests that blood cancers are more sensitive than solid tumors to anti-CD47:SIRPα therapies." (PMID 33552071, 2020). "In this regard there are several early phase clinical trials currently recruiting for combinations of CD47:SIRPα blockers + therapeutic antibodies for solid tumors and blood cancers." (PMID 33552071, 2020). "In blood cancer, several SIRPα-CD47 blockers have shown encouraging monotherapy activity." (PMID 38843278, 2024). "CD47 has emerged as a potential therapeutic target and is being investigated in various preclinical studies as well as clinical trials to prove its safety and efficacy in treating hematological neoplasms." (PMID 32677994, 2020). "Signaling lymphocyte activation molecular family 7 (SLAMF7) has been identified as a non-negligible component of CD47-mediated macrophage clearance of hematopoietic tumor cells." (PMID 37484024, 2023).
cardiovascular diseases (11 papers, 2015 to 2025). "Recent clinical studies evaluating drugs targeting CD47 in oncology have confirmed the emerging interest in TIPS/CD47 in human diseases other than cardiovascular disease." (PMID 37569855, 2023). "Therapeutic agents that block TSP1/CD47 signaling improve the sensitivity to NO-mediated vasodilators in cardiovascular diseases in humans as well as in pigs and rodents, where these agents improve blood flow and hyperemia in response to ischemia." (PMID 37569855, 2023). "In ischemic mouse models, exposure to CD47-blocking agents results in significant improvement of tissue survival and decreased vasculopathy, an evidence of the therapeutic value of CD47 suppression to treat cardiovascular disease." (PMID 28714932, 2017).
infectious disease (7 papers, 2019 to 2025). A disorder directly resulting from the presence and activity of a microbial, viral, or parasitic agent in humans. "In this review, we recapitulate anti-CD47 antibody as a potential therapeutic target for infectious diseases." (PMID 32882841, 2020). "This review highlights the immunotherapeutic targeted role of CD47 in the infectious disease realm." (PMID 32882841, 2020).
inflammation (6 papers, 2019 to 2025). Aberrant reaction of the microcirculation characterized by movement of fluid and leukocytes from the blood into extravascular tissues. "To validate this result in vivo, we assessed the expression of CD47 proteins on ILC2s in a mouse model of IL33-mediated airway inflammation." (PMID 39160226, 2024). "Pharmacological activation of CD47 has been shown to accelerate resolution of subretinal and peritoneal inflammation, with implications for treatment of chronic inflammatory diseases and possibly other conditions." (PMID 31185026, 2019). "Finally, the BAL of mice treated with CD47-Fc showed a reduction in hILC2-driven lung inflammation and fewer eosinophils compared to the control group." (PMID 39160226, 2024). "Importantly, treatment with either anti-CD47 or anti-SIRPα antibodies ameliorated liver inflammation and fibrosis by enhancing the clearance of necroptotic hepatocytes, suggesting that therapeutic blockade of the CD47-SIRPα axis acts as a strategy to dampen MASLD progression." (PMID 40494889, 2025). "Circulating markers such as IL-6, myeloperoxidase (MPO), MMP-9, hsCRP, CD47, and LDL cholesterol have demonstrated utility in characterizing chronic vascular inflammation." (PMID 41007845, 2025).
vasculopathy (5 papers, 2017 to 2025). "Initial experiments showed that loss or inhibition of CD47 prevented age- and diet-induced vasculopathy and reduced damage caused by ischemic injury in mice." (PMID 34698067, 2021). "Taken together, these findings indicate that CD47 signaling globally promotes aging by suppressing angiogenesis, and escalating vasculopathy and metabolic imbalance." (PMID 32679764, 2020). "The broad expression of IL-6, IL-17 and CD47/SIRP on erythrocytes, platelets, lymphohematopoietic cell, and endothelial and epithelial cells indicates their roles in cell differentiation, apoptosis, phagocytosis and cell-cell fusion, as well as many metabolic and vascular disorders." (PMID 41184328, 2025).
gastrointestinal tumors (4 papers, 2018 to 2025). "The results suggested that high CD47 expression was also associated with an adverse prognosis for digestive system tumors (HR = 1.90; 95% CI: 1.51–2.40; p < 0.00001)." (PMID 40765033, 2025). "CD47 is overexpressed in a majority of gastrointestinal tumors, and CD47 overexpression usually predicts an adverse prognosis." (PMID 33917794, 2021). "Conversely, it may also facilitate the progression of gastrointestinal tumors by modulating critical effector molecules such as CD47 and PD-L1." (PMID 40909948, 2025). "However, as summarized earlier, PD-L1 antibodies are used far more frequently than CD47 antibodies in gastrointestinal tumors." (PMID 40909948, 2025). "Considering the negative effect of anti‐CD47 mAb on host immune cells, the augmentation of macrophage phagocytic activity by anti‐SIRPα mAb may constitute an effective treatment for human gastrointestinal tumors." (PMID 30460349, 2018).
metabolic disease (4 papers, 2023 to 2025). A congenital disorder (due to inherited enzyme abnormality) or acquired (due to failure of a metabolically important organ) disorder resulting from an abnormal metabolic process. "Moreover, enhanced TSP1/CD47 signaling is associated with impaired tissue repair and chronic inflammation in cardiovascular and metabolic disorders." (PMID 41303525, 2025). "Moreover, administration of neutralizing antibodies targeting CD47 can alleviate the metabolic disorder in vivo caused by obese vWAT-Exos." (PMID 40016734, 2025). "In metabolic diseases, CD47 fosters adipose tissue inflammation, hepatic steatosis, and kidney lipotoxicity, while inhibiting pancreatic β-cell insulin secretion, whereas inhibition improves metabolic homeostasis and glucose regulation in preclinical models." (PMID 41303525, 2025). "Thus, CD47 deficiency appears to improve systemic metabolism by promoting BAT activation and WAT browning, offering protection against diet- and age-related metabolic disorders." (PMID 40630093, 2025). "Therefore, it is evident that blocking the SIRPα-CD47 axis can effectively inhibit obese vWAT-Exo-induced metabolic disorders, partly due to the clearance effect of vWAT-Exos." (PMID 40016734, 2025). "In addition, we found that blocking SIRPα-CD47 enhances macrophage phagocytosis of vWAT-Exos and thus alleviates metabolic disorders and tissue inflammation in obese mice." (PMID 40016734, 2025). "Additionally, we found that inhibiting the SIRPα-CD47 axis can mitigate metabolic disorders induced by obese vWAT-Exos or ob/ob mice, partly due to the enhanced clearance of vWAT-Exos." (PMID 40016734, 2025). "Addressing these issues may help advance our understanding of the link between CD47 and MASLD and promote its clinical application in metabolic diseases." (PMID 40630093, 2025).
adenocarcinoma (3 papers, 2022 to 2026). A common cancer characterized by the presence of malignant glandular cells. "A genome-wide analysis further confirmed that CD47 expression was significantly higher in NEPC tissues than in adenocarcinoma tissues." (PMID 41163221, 2025).
bacterial infections (3 papers, 2015 to 2024). "iii) CD47 neutralizing antibodies protect mice from secondary bacterial infection by blocking the direct interaction between CD47 and FnBP." (PMID 38693120, 2024). "By comprehensively exploring the role of CD47 in facilitating secondary bacterial infections, this study may pave the way for the development of innovative therapeutic approaches, ultimately leading to improved clinical outcomes for patients." (PMID 38693120, 2024).
neurodegenerative disease (3 papers, 2019 to 2024). A disorder of the central nervous system characterized by gradual and progressive loss of neural tissue and neurologic function. "Since CD11c+ microglia are characteristically observed in several neurodegenerative diseases, the CD47–SIRPα signal may be widely involved in the pathology of degenerative brain diseases through the control of the protective function of microglia." (PMID 30910011, 2019). "Consequently, further research pertaining to the specific functions and roles of CD47 and SIRP is required prior to its exploitation as a druggable approach for the targeting of various neurodegenerative diseases that affect the human population." (PMID 34203368, 2021).
renal disease (3 papers, 2020 to 2025). "Activation of Jun, a transcription factor in the JNK pathway, promotes transcription of genes involved in many fibrotic diseases, including renal disease, and is associated with increased expression of CD47, an anti‐phagocytic protein that promotes fibrosis." (PMID 40223398, 2025). "Blockade of CD47 restores efferocytosis of NETs and injured vascular endothelium, resulting in the improvement of renal disease in AAV." (PMID 37368493, 2023). "In our mouse study, anti-CD47 mAb was administered in the phase of disease development; as a result, it prevented renal disease with a reduction in proinflammatory gene expression, whereas it increased infiltrating neutrophils with macrophage activation." (PMID 37368493, 2023). "A recent study showed that CD47 colocalized with E-cadherin at the cell–cell adhesion sites of epithelial cells in HFD-induced kidney disease." (PMID 33681182, 2020). "Having shown that CD47 blockade ex vivo contributes to the clearance of NETs and injured endothelium via efferocytosis, we tested whether renal disease in AAV is abrogated by the systemic administration of anti-CD47 antibody." (PMID 37368493, 2023). "In histological analysis of human renal biopsy, patients with biopsy-proven MGA clinically presented with hematuria or proteinuria; therefore, they might be in subclinical phage of kidney disease, which could influence CD47 expression." (PMID 37368493, 2023).
kidney (2 papers, 2025). "In summary, the data presented here demonstrated that STAT3 and CD47 are two potential therapeutic targets for the treatment of OS lung metastases." (PMID 40529368, 2025).
neurological disorders (2 papers, 2021 to 2023). "Taken together, these discoveries encourage further testing and engineering of CD47 for the clinical management of different neurological disorders." (PMID 38125492, 2023). "During neurological disorders, CD47 functions as a key neuroimmune modulator responding to chronic and acute CNS injuries and in the process of recovery." (PMID 34203368, 2021). "During the development of neurological disorders, CD47 has been suggested to function as a key neuroimmune regulator in responding to chronic and acute CNS injuries and its recovery." (PMID 34203368, 2021). "The role of CD47 in neuronal development is an active area of research as it may be a target in treating a group of neurological disorders." (PMID 38125492, 2023).
heart diseases (1 paper, 2021). "Recently, multiple studies reported that CD47 is abnormally expressed in various heart diseases, resulting in damage to the cardiomyocyte surface, impaired macrophage phagocytotic activity, and reduced clearance of dead cells in the infarct area." (PMID 34349643, 2021). "Hence, exploring the regulatory mechanism of CD47 expression might provide a new therapeutic target for heart diseases." (PMID 34349643, 2021).